CAAP1 (caspase activity and apoptosis inhibitor 1)
Description:
Anti-apoptotic protein that modulates a caspase-10 dependent mitochondrial caspase-3/9 feedback amplification loop.
Synonyms: CAAP; C9orf82; FLJ13657
Tractability: PROTAC: UniProt records ubiquitination sites on it; ubiquitination databases record sites on it; its protein half-life has been measured.
Gene: Protein-coding gene on chromosome 9 (26,840,685 to 26,892,819, reverse strand). Ensembl gene ENSG00000120159.
Subcellular location (Human Protein Atlas): Vesicles
Gene Ontology:
Biological process: negative regulation of apoptotic process; regulation of apoptotic process
Genetic constraint (gnomAD): Loss-of-function variants: 10 observed, 14.93 expected, observed/expected ratio (o/e) 0.67, 90% interval 0.41 to 1.14. The synonymous counts are far from expectation, so gnomAD's model fits this gene poorly and the ratio says little. Missense variants: 403 observed, 339.83 expected, observed/expected ratio (o/e) 1.19, 90% interval 1.09 to 1.29. Synonymous variants: 169 observed, 135.11 expected, observed/expected ratio (o/e) 1.25, 90% interval 1.1 to 1.42.
Homologues: Orthologues: chimpanzee CAAP1 (99% identical), macaque CAAP1 (99% identical), dog CAAP1 (94% identical), pig CAAP1 (93% identical), guinea pig CAAP1 (91% identical), rabbit CAAP1 (89% identical), rat Caap1 (83% identical), mouse Caap1 (82% identical), tropical clawed frog caap1 (47% identical), zebrafish caap1 (38% identical), Drosophila melanogaster CG32176 (20% identical), Caenorhabditis elegans F15D4.2 (9% identical).
Diseases named in the same sentence as CAAP1 in open-access papers:
CAAP1 is named in the same sentence as 11 diseases in open-access papers, as found by Europe PMC text mining. Sharing a sentence is not in itself a finding about the gene and the disease. The quoted sentences say what the papers report.
gastric cancer (1 paper, 2022). A primary or metastatic malignant neoplasm involving the stomach. "Moreover, miR-5100 can increase the apoptosis level of gastric cancer cells and inhibit autophagy by targeting CAAP1 (conserved anti-apoptotic protein 1 or caspase activity and apoptosis inhibitor 1)." (PMID 36551682, 2022).
liver cancer (1 paper, 2022). An epithelial or non-epithelial malignant neoplasm that arises from the liver. "In this paper, CCK-8 experiment, clone formation experiment, flow cytometry, scratch experiment, and Transwell chamber experiment are used to analyze the effects of target gene CAAP1 on the proliferation, apoptosis, migration, and invasion of liver cancer cells." (PMID 35186067, 2022).
cancer (2 papers, 2011 to 2024). A tumor composed of atypical neoplastic, often pleomorphic cells that invade other tissues. "Contrary to the previous genes, the products RGN, CAAP1, and STAP1, have been found to exert an anti-apoptotic effect and the disruption in their expression was reported in many cancers." (PMID 38978053, 2024).
CAAP1 also shares sentences with these, for which no sentence is quoted: breast carcinoma (2 papers); tumor (2); Cerebral ischemia (1); infection (1); lung carcinoma (1); Sézary syndrome (1); transient cerebral ischemia (1); triple-negative breast carcinoma (1).